TNF (tumor necrosis factor)
Diseases named in the same sentence as TNF in open-access papers (continued):
Sharing a sentence is not in itself a finding about the gene and the disease.
cancer (continued). "Via rising distal natural killer (NK) cells and inducing cancer‐specific CD8+ T cells with specific memories, lowering pro‐inflammatory cytokines including TNF and IL‐17, and through boosting the quantity of Th17 lymphocytes and FOXP3 in circulation within cancer mattresses." (PMID 38571678, 2024). "During treatment with PD-1/PD-L1 inhibitors, TIM-3 upregulation may suppress T helper cell type 1 (Th1) cell responses and decrease the expression of cytokines like TNF-α and IFN-γ, leading to drug resistance in cancer patients." (PMID 38524135, 2024). "It was also observed that individuals from subtype 2 were enriched in various cancer-related pathways including the JAK-Stat signaling pathway, TNF signaling pathway, and NF-kB signaling pathway indicating the worst survivability of subtype 2 compared to subtype 1." (PMID 38172584, 2024). "Other cancer-related KEGG terms such as Metabolic pathways (p-value = 5.90 × 10−6), Cytokine–cytokine receptor interaction (p-value = 3.0 × 10−3), and TNF signaling pathway (p-value = 7.03 × 10−3) were also enriched in ISO-upregulated genes, which was consistent with our GO analysis." (PMID 38339062, 2024). "MiR-100-5p and miR-138-5p: Studies have shown that miR-100-5p and miR-138-5p are related to mitogen-activated protein kinase (MAPK) signaling pathway, apoptosis, and tumor necrosis factor (TNF) pathway, all of which are the regulators of cancer development, progression, and immune escape." (PMID 38605944, 2024). "CD8+ T lymphocytes could directly destroy cancer cells by releasing cytotoxic granules, such as granzyme B and cytokines, such as IFN‐γ and TNF‐α." (PMID 39267250, 2024). "Human-derived cytokines interleukin-2 (IL-2), IL-4, IL-6, IL-12, IL-10, tumor necrosis factor α (TNF-α), and interferon-γ (IFN-γ) could be detected in all cancer cell–bearing mice by cytokine level measurement." (PMID 39606226, 2024). "The tumor suppressor PTEN and the tumor necrosis factor (TNF) were the second (degree = 54) and third (degree = 53) more connected nodes, respectively, and like MYC, they both play a role in various types of cancer." (PMID 39595075, 2024). "By unveiling the role of TGF-β and TNF-α in promoting MMP-9 expression through epigenetic modifications, we provide a foundation for future investigations into the complex molecular interactions that drive cancer metastasis." (PMID 39351229, 2024). "Clinical trials of agents targeting TNF‐α in patients with cancer cachexia are not conclusive, while those targeting both IL‐6 and TNF‐α show greater promise." (PMID 38481033, 2024). "CTLs produce tumor necrosis factor (TNF), granzyme, and perforin to exert cytotoxic activity against HCC cells, and some remain memory-killer cells, carrying a mechanism that recognizes the same cancer cells." (PMID 39769351, 2024). "Degradation of IAP proteins by an IAP antagonist does not effectively kill cancer cells but enables TNFα to strongly induce cancer cell apoptosis." (PMID 39105847, 2024). "Thus, the anti-cancer and anti-inflammatory action of 10-HDA was mediated through the reduced production of pro-inflammatory cytokines (TNF-α, IL-1β, and IL-8)." (PMID 38892209, 2024). "The pro-inflammatory mediators TNF-α and IFN-γ also play an important role in the communication and activation of adaptive immunity, especially by stimulating Th1 cells, which are important for the elimination of cancer cells." (PMID 39065638, 2024). "Conversely, due to its pleiotropic function (as cytokine and adipokine) and conflicting role in cancer, TNF-α concentrations had no prognostic effect." (PMID 38989743, 2024). "During the membrane shedding process, MMPs cleave several signaling molecules and release their ectodomains such as tumor necrosis factor (TNF-α) and transforming growth factor (TGF)-β from the cell membrane, which enhances the survival and migration of cancer cells." (PMID 38317965, 2024).
cancer (continued). "IFN-γ and TNF-α were investigated from the supernatant of co-cultured CAR-T and cancer cells." (PMID 38700775, 2024). "Small molecule inhibitors of apoptosis proteins (IAPs) antagonists, known as Smac mimetics (SMs), activate non-canonical NF-κB and sensitize cancer cells to TNF-induced cell death." (PMID 39578442, 2024). "Therefore, targeting tumors to deliver TNFα locally, combined with an IAP antagonist, would be an attractive approach to eliminate cancers strongly and specifically with fewer side-effects." (PMID 39105847, 2024). "On the one hand, the anticancer property of TNF-α is to induce cancer cell death, but on the other hand, TNF-α also stimulates cell proliferation, migration and angiogenesis and is highly overexpressed in many cancers." (PMID 38200509, 2024). "Meanwhile, KEGG analysis showed that the following pathways were significantly enriched: cytokine–cytokine receptor interactions, the interleukin (IL)-17 signaling pathway, the tumor necrosis factor (TNF) signaling pathway, and transcriptional dysregulation in cancer." (PMID 38965537, 2024). "Additionally, TNF-α potentiates the activity of IL-6, which activates STAT3 expression in cancer cells, enhancing the self-renewal and invasive capabilities of pancreatic cancer stem cells." (PMID 39680287, 2024). "Following the analysis, 16 genes were then subjected to the network and pathway analyses, which revealed that these genes are involved in several cancer-related pathways including Jak-stat signaling, MAPK cascade, epidermal growth factor signaling, TNF signaling pathways, and many others." (PMID 38172584, 2024). "The efficacy of the ACT in treating cancers depends on the engineered cell production of a wide variety of cytokines, including interleukin-IL-2 (IL-2), IL-4, IL-6, TGF-β, interferon-γ, tumor necrosis factor-α (TNF), IL-8, and IL-10, IL-15, IL-18, IL-21, etc.." (PMID 39105847, 2024). "CD8+ T cells not only directly kill cancer cells via perforin and granzyme pathways or the Fas/Fas ligand pathway but also indirectly destroy tumors through secreting cytokines such as IFN-γ and TNF-α." (PMID 39108262, 2024). "In cancer patients receiving n-3 LCPUFAs from fish oil supplements, inflammatory cytokines, including interleukin- 6 (IL-6), C-reactive protein (CRP) and tumor necrosis factor-alpha (TNFα), were found to be lower than those in control groups." (PMID 38308227, 2024). "We also noticed that in advanced stages of OC and in primary carcinoma tissues with metastatic potential, RONS can activate NF-κB activity by reducing the expression of its inhibitory protein (IκB) to promote inflammatory response (↑ TNFα)." (PMID 38397798, 2024). "Within those, NK cells have a key role in anti-cancer immunity as they are an active component of the innate immune system and produce cytokines like interferon-gamma (IFN-γ) and tumor necrosis factor-alpha (TNF-α)." (PMID 38132355, 2023). "Amongst them, 160 were exposed to biologics (34 VDZ, 27 USK, and 99 anti-TNFα) after the diagnosis of cancer and 181 received no immunosuppressive treatment." (PMID 36672491, 2023). "Due to these reasons, the effects of anesthesia on TNF-α release and resultant cancer outcomes eventually become minimal or none." (PMID 36765695, 2023). "Moreover, Shemlali preparations regulated the expression of Cox1 (up-regulation) and TNF-α (down-regulation) on HCT-116 cells, revealing their efficiency in suppressing the expression of genes that promote cancer cell proliferation." (PMID 38109310, 2023). "The crude cancer incidence rate per 1000 person-years for the full follow-up period was 7.5 (95% CI: 6.4–8.7) in the SOT/HSCT, 8.0 (95% CI: 7.3–8.8) in the PID/SID, and 3.4 (95% CI: 2.7–4.3) in the TNF-i cohort." (PMID 36624408, 2023). "There was no increase in the risk of new or recurrent cancer with VDZ (HR 1.38, 95% CI: 0.38–1.36) or anti-TNF therapy (HR 1.03, 95% CI: 0.65–1.64) when compared to non-immunosuppressive therapy." (PMID 36983432, 2023).
cancer (continued). "Moreover, GM-CSF, TNF-α, MMP-2, MMP-9, and proinflammatory cytokines such as IL-1β and IL-6 are involved in NF-κB and AP-1-mediated cancer progression." (PMID 37298797, 2023). "There was no statistical difference in the adjusted (after matching on age, lymph nodes, metastasis, and Penn’s classification) cancer incidence rates per 1000 p-y in patients under anti-TNFα, VDZ, and no treatment (41.4, 33.6, and 40.9, respectively)." (PMID 36672491, 2023). "TNF-α is a pro-inflammatory cytokine that can be secreted by TAM and cancer cells." (PMID 37765264, 2023). "In conclusion, in the majority of the studies, anti-TNFα therapy seems to not increase the rate of new or recurrent diagnosis of cancer in patients with previous diagnosis of cancer." (PMID 36672491, 2023). "In particular, this trial evaluated the hypothesis that the risk of major adverse cardiovascular events or cancers, excluding non-melanoma skin cancer, would not be at least 1.8 times higher with tofacitinib (combined doses of 5 mg and 10 mg twice daily) than with a TNF inhibitor." (PMID 37190126, 2023). "EtOAc No. 001 and Hex No. 008 showed excellent cancer prevention properties by inhibiting TNFα and NO production when compared with a positive control (dexamethasone)." (PMID 37296375, 2023). "In addition, siRNA-SCCNVs were produced from B16F10 cancer cells that were treated with doxorubicin and transfected with siRNAs specific for IFN-γ and TNF-α." (PMID 36854774, 2023). "Notably, TNF‐α and IFN‐γ, as signaling axes regulating PANoptosis, can induce cell death in various human cancer cell lines, including lung, colon, and leukemia." (PMID 38069556, 2023). "The role of PURA in cancer, in particular, in transcriptional regulation, is complex and context dependent; for example, PURA can function as a transcriptional activator for some genes, including TGFβ1,53 TNFα,54 and β2-integrin." (PMID 37149929, 2023). "Our previous reports found out TCPT activated inflammation in H22 tumor bearing mice through producing IL-2 and TNF-α, which imply TCPT might be a pro-inflammatory factor in cancer treatment." (PMID 36597133, 2023). "Fractalkine, TNFα, SCF, and other cytokines were increased/decreased in patients with risks versus no risk and in female versus male with risks, except in cancer treatment and immunosuppressed patients." (PMID 37998327, 2023). "In terms of KEGG pathway enrichment analysis, significantly enriched pathways included cytokine-cytokine receptor interaction, pathways in cancer, PI3K-Akt signaling pathway, chemokine signaling pathway, TNF signaling pathway, IL-17 signaling pathway and NF-kappa B (NFκB) signaling pathway." (PMID 36860851, 2023). "These targets are involved in multiple signaling pathways, including a variety of cancer pathways, the PI3K-Akt signaling pathway and the TNF signaling pathway, and participate in BP, mainly consist of apoptosis, oxidative reaction and, transcriptional regulation." (PMID 37832105, 2023). "To address the mechanism of action of glucocorticoids on cancer cells in an inflammatory context, we examined the effect of dexamethasone in the presence or absence of the cytokine Tumor Necrosis Factor-α (TNF-α)." (PMID 36900323, 2023). "Both TNF-α and IFN-γ enhanced mICAM-1 expression and induced release of sICAM-1 in all cell lines tested suggesting this mechanism in generalizable across different cancer types." (PMID 37732732, 2023). "DMBA-induced mammary gland carcinoma as marked by an elevation of mRNA level of cancer promoter genes (Serpin and MIF, LOX-1, and COL1A1) and serum level of VEGF, TNF-α, TGF-β, CA15-3, and caspase-3 with the reduction in mRNA level of suppressor gene (FST and ADRP)." (PMID 35138531, 2023). "Besides chemokines of NF-κB signaling, the inflammatory cytokines TNF-α and LIF were highlighted to play a role in interaction with CXCL-8 in cancer development and the chemokines CXCL3 and CXCR2 in their role in cell migration." (PMID 37048115, 2023).
cancer (continued). "Previous studies in various types of cancer have shown that treatment with Smac mimetic monotherapy can induce the expression and secretion of TNF-α via a non-canonical NF-κB signaling." (PMID 37513508, 2023). "These proteins have different types of substrates, including cancer-related proteins, such as NOTCH receptor and ligand, epidermal growth factor receptor (EGFR) ligand, interleukin-6 receptor (IL-6R), tumor necrosis factor (TNF) and its receptor, E-cadherin and CD44." (PMID 37370817, 2023). "Moreover, compared to those obtained from the circulation of the cancer patients, the lymph node‐derived PD‐1+CXCR5+ cytotoxic T cells displayed considerable capacities to secrete TNF‐α and especially IFN‐γ." (PMID 38069525, 2023). "KEGG pathway enrichment analysis involved mainly 178 signaling pathways, such as cancer signaling pathway, AGE-RAGE signaling pathway, interleukin-17 signaling pathway, tumor necrosis factor signaling pathway, endocrine resistance signaling pathway, cell aging signaling pathway, and so on." (PMID 38206683, 2023). "Incident-cancer-free survival rates were not different between patients receiving anti-TNF and those receiving VDZ, p = 0.56." (PMID 36983432, 2023). "The top 25 KEGG pathways included Cytokine-cytokine receptor interaction, IL-17 signaling pathway, Toll-like receptor signaling pathway, TNF signaling pathway, MAPK signaling pathway, mTOR signaling pathway, NF-κB signaling pathway, JAK-STAT signaling pathway, and Pathways in cancer." (PMID 37381044, 2023). "Out of these, 77 patients never interrupted the anti-TNFα therapy after the diagnosis of the index cancer and 30% were also exposed to thiopurines or methotrexate after the diagnosis of the index cancer." (PMID 36672491, 2023). "No cytotoxic effects (p < 0.05) were observed when cancer cells were treated with the cytokines at the following concentrations: 500 U/mL IFNα, 500 U/mL IFNβ, 20 ng/mL TNFα, and 100 U/mL IFNγ." (PMID 37760788, 2023). "Interestingly, plasma VEGF-A, TNF-α, CCL2, IL-6, and IFN-γ cytokines levels were significantly enhanced in the Untreated Cancer TIF1-γ-DM group than in the Non-cancer TIF1-γ-DM group." (PMID 36357631, 2023). "Barring a few studies, no prognostic effect of the administration of anti-TNFα mAb to patients with cancer has been observed in most studies." (PMID 36996146, 2023). "It was also observed that TNF-α, CASP8, CLIP3, and STAT1 are characteristics of G2 and G3 cancer." (PMID 37233761, 2023). "Furthermore, feladilimab enhanced the production of IFNγ, IL17, IL10, and TNFα by TCR-activated healthy donor and cancer patient PBMC." (PMID 37593752, 2023). "In addition, the expression levels of IL-6, IL-17, TNF-α,IL-12β, TLR-2, and TLR-4 as well as miR-21 and miR-31 showed a significant increase in the cancer group." (PMID 38075864, 2023). "In one, patients with previous cancer were categorised into four cohorts (none, conventional immunosuppressant, anti-TNF, or vedolizumab) according to the first treatment to which they were exposed after the index cancer." (PMID 36831424, 2023). "Moreover, TNF-α has been shown to induce TGFB overexpression, which eventually promotes cancer cells to migrate." (PMID 37261338, 2023). "PML, C3, TXN, KRT6C, F2, PTK2, TNF, which could enable HIF-mediated inflammatory response during cancer development." (PMID 36845724, 2023). "TNF-α stimulates Snail1 promoter activity, EMT, and protein stabilization in cancer cells." (PMID 37598126, 2023).
cancer (continued). "Interestingly, ERK5 inhibition also sensitized EC cells to the toxicity induced by other DR ligands such as TNFα or FasL, indicating a role for ERK5 kinase activity in mediating the extrinsic apoptosis induced by DR agonists in cancer cells." (PMID 37919293, 2023). "Treating 4T1 and MCF10A H-RasV12 cancer cells with TNFα increased spheroid growth even without extra palmitate, while NF-κBi treatment decreased spheroid growth in the presence of extra palmitate." (PMID 36732635, 2023). "Additionally, MSCs are involved in the progression of cancer cells by releasing active molecules such as SDF-1, CCL5/CCR5, CCR2, TNF-α, TGF-β, etc.." (PMID 38022534, 2023). "However, the roles of the TNF-α and IFN-γ expressions in regulating merisis and metastases of cancer in LUAD remain to be determined." (PMID 36865498, 2023). "The MTD of targeted TNF is 5–10 times lower than that of targeted IL2 in mice and cancer patients." (PMID 37092450, 2023). "Through the PI3K-Akt, HIF-1, and ErbB signaling pathways, curcuma regulates key targets that are involved in angiogenesis, cancer cell proliferation, metastasis, invasion, and chemotherapy resistance, including AKT1, TNF, STAT3, EGFR and HSP90AA1, in the treatment of OS." (PMID 37311820, 2023). "Studies have shown that chemokines and cytokines, such as TNF-α, IL-2, and chemokine CCL2, play a role in the formation of the cancer microenvironment and are responsible for the migration of inflammatory cells and cancer cells." (PMID 37968670, 2023). "Research on the TNF-α release and its impact on cancer cell biology with the exposure to VAs is lacking." (PMID 36765695, 2023). "The concentration of TNF-α was found to be increased significantly in the negative control group (p < 0.001) due to cancer induction in comparison to the control vehicle group." (PMID 38067358, 2023). "The other compared 96 patients exposed to vedolizumab after a prior diagnosis of cancer to 184 and 183 patients exposed to anti-TNF or no immunosuppressive therapy, respectively." (PMID 36831424, 2023). "We speculate that patients with higher TNFα are able to kill the ACC and STAG cancer stem cells selectively, indicating that the surviving cells might persist longer in healthy patients." (PMID 37047540, 2023). "By contrast, biNV could stimulate CD8+ T cells to generate increased levels of IFN-γ and TNF-α, leading to a higher rate of T cell-mediated cytolysis against 4T1 and CT26 cancer cells." (PMID 37875481, 2023). "In addition, the results showed that the mRNA expressions of TNF-α and IFN-γ in cancer tissues were lower than those in paracancerous tissues and normal tissues." (PMID 36865498, 2023). "BTCEs work by harnessing the patient own immune system to induce T cell mediated cytotoxicity against malignant cells through the production of inflammatory cytokines such as TNF-α and IFN-γ and the release of perforin and granzyme which in turn led to the killing of cancer cells." (PMID 37143061, 2023). "CD70 is a member of the tumor necrosis factor (TNF) superfamily and has recently been considered as a potential target for AML; the normal expression of CD70 is restricted to activated immune cells, but its expression is increased in many cancer types." (PMID 36835136, 2023). "Our results were consistent with this finding which further revealed that plasma TNF-α levels in the Cancer TIF1-γ-DM group were significantly higher than in the Non-cancer TIF1-γ-DM and HC groups." (PMID 36357631, 2023). "Our GSEA results revealed that the DEGs were inversely correlated with several cancer-related signaling pathways such as HIF-1 signaling, TNF signaling, NF-kappa B signaling, ferroptosis, and IL-17 signaling, which was in agreement with the functional GO and KEGG pathway enrichment analysis." (PMID 37350944, 2023). "Additionally, KLRB1 expression was observed to involve the cancer pathways (such as the NF-κB, PI3K-Akt, and TNF pathways)." (PMID 37988189, 2023).